PTK2 (protein tyrosine kinase 2)
Diseases named in the same sentence as PTK2 in open-access papers (continued):
Sharing a sentence is not in itself a finding about the gene and the disease.
tumor (continued). "Furthermore, mapping drug target data to the top genes in our association prediction identifies inhibitors that could potentially enhance tumor response to anti-PD1, such as inhibitors of the encoded proteins of CDK4, GSK3B, and PTK2." (PMID 35013211, 2022). "Activation of PTK2 might be an important step in tumor cell growth and interactions with the ECM." (PMID 29285246, 2017). "Immune cell infiltration landscapes were characterized using CIBERSORT and ssGSEA algorithms, while the Tumor Immune Dysfunction and Exclusion (TIDE) computational framework was applied to predict HCC responsiveness to ICIs based on PTK2 expression." (PMID 41727972, 2025). "10%–14% of primary tumor samples exhibited copy number gain and aberrant mRNA expression in both FAK (PTK2) and SRC, consistent with prior studies." (PMID 40959971, 2025). "Seven GRPGs (PIM2, PGK1, ADPGK, YWHAZ, PTK2, PGAM1, and VDAC1) were significantly upregulated in the TCGA-BRCA tumor tissues." (PMID 40046063, 2025). "We observed that kinase activity profiles varied between tumor intrinsic subtypes, with a highly hyperactive Phos2 (hyperactivity of PI3K/AKT and mTOR signaling members, PTK2, SRC, EPHA2 kinases) and a less active Phos1 subtype." (PMID 38650175, 2024). "These included PTK2, also known as focal adhesion kinase (FAK), which is reported to engaged in the progression of various tumor types." (PMID 37875515, 2023). "The median survival probability in a cohort of patients with high gene expression versus low gene expression in tumor specimens was 12.94 months vs. 16.79 months (p = 0.009) for PTK2B and 12.58 months vs. 13.63 months (p = 0.0275) for PTK2." (PMID 37686276, 2023). "Representative IHC staining of KLF7, TLR4, and PTK2 in HCC tissues and adjacent non-tumor tissues is presented." (PMID 37554278, 2023). "On the other hand, the identified genes with notable decreased mRNA levels playing roles in tumor growth promotion were USP12, CAT and PTK2 (FAK)." (PMID 36077645, 2022). "Increased expression of FAK (governed by the PTK2 gene) is considered to be a prognostic marker in PDAC and is positively correlated with tumor size." (PMID 35628269, 2022). "circ-PTK2 affects the miR-330-5p/forkhead box M1(FOXM1) axis by binding to miR-330-5p, accelerating tumor progression, and inhibiting tumor apoptosis." (PMID 35795049, 2022). "Among the downregulated genes were several known to activate proliferation of tumor cells (NOTCH1, HMGA2, PTK2, FOSL1, GREM1 and EGR1)." (PMID 35885035, 2022). "Recent comprehensive proteogenomic analysis of OC tissues revealed that autophosphorylation status of PTK2 (pY397) and PTK2B (pY402) was altered in tumor tissues." (PMID 31442208, 2019). "The high levels of PTK2 and Src, known regulators of cell migration, alongside significant correlation between Src and p63 in OPSCC tumours, implicates Src signalling in the invasive of E6/E7-HFK." (PMID 26001294, 2017). "Through the basis of annotation suggesting that PTK2, CTTSL1, TNC, ETS1 and HSP90AA1 were involved in tumor cell proliferation, prevent tumor cell from apoptosis and promote tumor cell invasion in oral carcinogenesis." (PMID 23405089, 2013). "In addition, GSE29044 had more differentially expressed GRPGs between normal and tumor tissues (CS, PGK1, HNRNPA1, ADPGK, YWHAZ, PTK2, and PGAM1) than GSE42568 (CS, HNRNPA1, ADPGK, and PTK2)." (PMID 40046063, 2025). "Although FAK/PTK2 is not closely associated with age (13/33), gender (5/33), or tumor stage (5/33) in any of the studied human cancers, it has potential prognostic value for predicting patient survival." (PMID 38518034, 2024). "To better understand the role of FAK/PTK2 in cancer immunotherapy, we analyzed its correlations with tumor microenvironment and with immune processes/elements (e.g., immune cell infiltration, immunosuppressants, and stimulants) and major histocompatible complexes." (PMID 38518034, 2024).
tumor (continued). "This weakens ASE of PTK2 mediated by SRSF1 (the effector of SRSF1 carcinogenic activity), leading to a decrease in PTK2 mRNA and protein expression, and thereby inhibiting cell proliferation, migration, and survival in tumor progression." (PMID 38302461, 2024). "Also known as protein tyrosine kinase 2 (PTK2), focal adhesion kinase (FAK) plays a vital role in tumor invasion and metastasis." (PMID 37894550, 2023). "Furthermore, antigen-dependent antibody-promoted interactions between monocytes and tumor cells were important for the induction of pro-inflammatory signals and CSPG4 IgE ADCC was impaired by a PTK2 inhibitor." (PMID 37185332, 2023). "Notably, there was a positive association between the levels of ARGs and CNV alteration; for example, the expression levels of PRG2, SERPINA5, and THBD were low in tumor tissues, while VEGFA, PF4, and PTK2 were expressed at high levels." (PMID 37938164, 2023). "Lastly, in CR-TNBC patient P942, the baseline PDX tumor (BTY14) had high phosphorylation on the shared pTyr sites of SRC, FYN, LCK, YES1, and FGR as well as SFK substrates such as tensin, SHIP-1 (INPP5D), AFAP1L2, paxillin, and PTK2." (PMID 36077757, 2022). "The tumor was then analyzed using HE and immunohistochemical staining, which showed that the cell number and density were greater in the circ-PTK2 overexpression group than those in the negative control group." (PMID 34034740, 2021). "However, during energy starvation, RB1CC1 is activated by ULK1 and inhibits focal adhesion kinase PTK2/FAK, leading to reduced cell motility and tumor metastasis." (PMID 34829881, 2021). "Some of these genes, which interfere with tumor cell growth/differentiation/migration/invasion (such as MYC, MET, PROM1, and PTK2), induce hypoxia (such as ARNT2, HIF3A, TGB2, MMP2, and POSTN) and genes regulating transcription via acetylation were downregulated upon pembrolizumab treatment." (PMID 32616706, 2020). "In ID8hPON2 cells, the expression profile of many genes known to regulate tumor growth including BRCA1, cyclin and cyclin-dependent kinase 20, PTK2, Hypoxia-upregulated protein 1, p21-activated kinase 3, IL-18, IL-33, IGF-1, IGFBP2 and RNA-binding protein 9, were identified." (PMID 29531225, 2018). "Aberrant activation of PTK2, a non-receptor tyrosine kinase that is involved in focal adhesion, has been recognized as a key mediator of anoikis resistance in variety of tumor cells." (PMID 27495308, 2016). "During tumour development and in particular during metastasis, the inactivation of CDH1 or alternatively the activation of PTK2 could be two disjoint paths to achieve cell migration to distant sites." (PMID 26427375, 2015). "Interestingly, KCNMA1, a critical tumor suppressor in GC has been shown to be inactivated by promoter region hypermethylation, and the anti-tumor effect of KCNMA1 is mediated through suppressing the expression of PTK2." (PMID 31959204, 2020). "Besides, ALT impairs the angiogenesis and tumor growth by down-regulating vascular endothelial growth factor receptor 2 (VEGFR2) phosphorylation level and its downstream protein kinases, including phospholipase C gamma 1 (PLCγ1), protein tyrosine kinase 2 (FAK), SRC, and AKT." (PMID 34899346, 2021).
cancer (1,166 papers, 2003 to 2026). A tumor composed of atypical neoplastic, often pleomorphic cells that invade other tissues. "Although mutations in PTK2 are uncommon in human cancers, its amplification is more often detected in human cancer." (PMID 40832091, 2025). "This research aimed to explore the underlying association between focal adhesion tyrosine kinase (FAK/PTK2) and cancer immunotherapy in 33 human cancers." (PMID 38518034, 2024). "To conclude, the studies show that the Fak protein and its gene [ptk2] are significantly associated with cancer progression." (PMID 36060520, 2022). "Cancer-associated ECs also expressed more PTK2 and FAK protein as well as higher levels of phosphorylation." (PMID 36158681, 2022). "The changes in ptk2 gene expression are associated with the pathological stage, progression, and cancer's specific survival." (PMID 36060520, 2022). "Higher PTK2 expression is associated with cancer progression, metastasis, and poor overall survival." (PMID 35137551, 2022). "Upregulation of PTK2 expression in cancer has been linked to malignant progression and poor prognosis." (PMID 36533074, 2022). "The human gene PTK2, encoding FAK, is localized at chromosome 8q24.3, a region characterized by frequent aberrations in human cancers." (PMID 31973707, 2020). "Potential pathways associated with FAK/PTK2 signaling in cancers were also explored." (PMID 38518034, 2024). "Cancer cells have been found to avoid apoptosis and choose cellular pathways associated with proliferation, motility, adhesion, and migration, where the overexpression of PTK2 and IRS1 proteins plays a role in survival." (PMID 38202644, 2023). "PTK2 encodes a cytoplasmic tyrosine kinase, central to several proliferative pathways, including integrin, G-protein coupled, and receptor tyrosine kinase signaling, and thus has a plausible role in cancer biology." (PMID 16457699, 2005). "In addition, PTK2 was also suggested to be associated with cancer development." (PMID 24223781, 2013). "Protein tyrosine kinase 2 (PTK2) is highly expressed in many cancers and is involved in cell growth, survival, migration, and invasion." (PMID 40046063, 2025). "Recent studies have found that PTK2 has been found to regulate cell proliferation and migration in various cancers, making it a potential target for drug development and disease treatment." (PMID 40040719, 2025). "The RNA expression of FAK (PTK2) was significantly overexpressed (foldchange > 2) in 71.5% (68/95) of the cancer tissues." (PMID 40958869, 2025). "This study extracted potential values of FAK/PTK2 in various cancers, especially in the context of immunotherapy." (PMID 38518034, 2024). "Research on the immunotherapeutic value of FAK/PTK2 in 33 human cancers provides evidence regarding the function of FAK/PTK2 and its role in clinical treatment." (PMID 38518034, 2024). "Gene profile analysis of the Pan-Cancer Genome Atlas dataset from GEPIA revealed that FAK (PTK2) expression was significantly increased in HCC compared with 31 other cancer types." (PMID 38560575, 2024). "There has been less research on the potential applications of PTK2 and theβ-catenin pathway in cancer therapies." (PMID 37875515, 2023). "More importantly, NRSN2-AS1 exerted a pro-cancer effect in OC cells through stabilizing PTK2 and subsequently promoted PTK2/β-catenin pathway activation." (PMID 37875515, 2023). "PTK2, also known as focal adhesion kinase (FAK), activates Wnt/β-catenin signaling and promotes cancer stem cell characteristics." (PMID 37190239, 2023). "The most prominent adhesion related cancer targets, whose inhibition caused cytotoxicity and radiosensitization, were integrin β1 (ITGB1), Focal adhesion kinase (FAK; PTK2) and Particular Interesting New Cysteine-Histidine rich protein (PINCH1; LIMS1)." (PMID 37206618, 2023). "While mutations in the PTK2 gene are uncommon, amplification of the gene and increased FAK expression are frequently observed in a variety of cancers." (PMID 37754230, 2023).
cancer (continued). "PTK2 is highly expressed in many cancers and is involved in cell growth, survival, migration, and invasion." (PMID 36533074, 2022). "PTK2 is considered a positive regulator in the progression and metastasis of various types of cancer." (PMID 36533074, 2022). "Some studies have shown a gradual increase in FAK protein (ptk2 gene) related to poor cancer prognosis." (PMID 36060520, 2022). "PTK2 is reported to take part in various singling pathways that promote cancer growth and metastasis through kinase-dependent control of cell motility, invasion, cell survival, and transcriptional events promoting epithelial to mesenchymal transition (EMT)." (PMID 35646067, 2022). "To assess the expression of PTK2 in cancer, we examined gene profiles from dataset in the TCGA’s Pan Cancer Atlas (The Cancer Genome Atlas)." (PMID 35574330, 2022). "PTK2 gene expression in human cancers and normal tissues was assessed using the TIMER online database." (PMID 36533074, 2022). "The expressions of the cancer-promoting PTK2 and PLEC genes were significantly higher in the C1 subgroups than the C2 subgroups." (PMID 35712127, 2022). "Inhibition of signal transduction pathways, such as vascular endothelial growth factor (VEGF) (which is capable of reducing cancer cell blood supply), FAK (PTK2); MMPS and Zxb1, reduces the formation of metastases." (PMID 35884991, 2022). "One FAK overexpression mechanism that has been identified in cancer is the copy number amplification of the 8q24.3 region containing the PTK2 locus, which is adjacent to the MYC locus." (PMID 35163650, 2022). "Some studies have shown that high expression of PTK2 and TIMP1 is associated with poor progression-free survival in patients with various cancers." (PMID 36158681, 2022). "PTK2 is located within the same genomic locus (8q24) as ASAP1, which is a region associated with aggressive cancer phenotypes, recurrence, and metastasis." (PMID 35574330, 2022). "Both AGO2 and PTK2 are located on chromosome 8q24.3, which is among the most frequently amplified regions in human cancers." (PMID 35163650, 2022). "In this study we demonstrated that PTK2 gene copy numbers are highly amplified and expression level is upregulated in multiple cancer types with the most upregulation in OC." (PMID 35574330, 2022). "Their Kaplan–Meyer analysis also showed a correlation between ptk2 gene expression and the pathological stages, invasion of the disease, and reduced chance of survival in carcinoma." (PMID 36060520, 2022). "Because of the involvement of PTK2(FAK) in many cancers, drugs that inhibit FAK are being sought and evaluated." (PMID 33909629, 2021). "Overexpression of Ptk2, which encodes FAK, improves cell migration, invasion, adhesion, proliferation, and survival in ovarian and other cancers." (PMID 34305583, 2021). "Three circRNAs (hsa_circ_0005273, hsa_circ_0008305, and hsa_circ_0003221) derived from the same pre-mRNA PTK2 were reported to participate in the progression of cancers, we aimed to test which circRNA is differentially expressed in LSCC samples." (PMID 34691176, 2021). "The most mutated gene was Protein tyrosine kinase 2 (PTK2), which was mutated in 813 cancer samples in multiple studies (7.4% of the 10 967 samples)." (PMID 34296749, 2021). "The FAK/PTK2 is kinase protein play crucial role in multiple cancer-related pathways activated by various surface proteins integrin and growth factor receptor." (PMID 34262595, 2021). "Somatic mutations hit genes wired to cancer proliferation, survival, and migration pathways, in the first place Ras/MAPK, PI3K-AKT, in addition to JAK/STAT (PIK3R1 and PTK2)." (PMID 32321919, 2020). "A range of PTK2 inhibitors are being tested in clinical cancer trials, with 40 studies currently registered (clinicaltrials.gov, 2020), including one study in patients with head and neck cancer." (PMID 32670895, 2020).
cancer (continued). "The kinase-dependent and kinase-independent functions of PTK2 moderate cell movement, invasion, survival and cancer stem cell self-renewal." (PMID 28231797, 2017). "Using this approach, 543 candidate cancer genes have been detected, and 75 of them, including MLL3 and PTK2, have known mutations in human pancreatic cancer patients." (PMID 29156578, 2017). "The role of PTK2 as a major player in suppressing the apoptosis of cancer cell has been well revealed, and PTK2 is often expressed at aberrant high levels in cancer cells." (PMID 28231797, 2017). "Focal adhesion kinase (FAK), also named Protein-tyrosine kinase 2 (PTK2), is the key regulator of UAs-related proteins involved in focal adhesion pathway, and also the key signal molecule associated with cancer metastasis." (PMID 25823660, 2015). "PTK2 was the most frequently gained gene on both the kinase and cancer-related gene list, amplified in 37/47 primary tumors (79%) and 15/18 cell lines (83%)." (PMID 16457699, 2005). "Crucially, the compartmentalized expression of COL1A2 in matrix cancer-associated fibroblasts and PTK2/FAK activation in epithelial cells undergoing epithelial–mesenchymal transition suggests a paracrine signaling paradigm that transcends traditional cell-autonomous frameworks." (PMID 41561769, 2025). "PTK2 (Protein Tyrosine Kinase 2) has traditionally been considered pro-oncogenic in many cancers, but recent evidence suggests context-dependent functions that may explain its association with improved survival in our cohort." (PMID 41356219, 2025). "Our analysis focused on the interaction dynamics between COL1A2/ECM-high matrix cancer-associated fibroblasts (matrixCAFs) and PTK2 (FAK)-high Epithelial_EMT cells, hypothesized as critical mediators driving the transition from NMIBC to MIBC." (PMID 41561769, 2025). "FAK protein is encoded by the PTK2 gene, which shows high copy number amplification across different cancer types, indicating that FAK may play an important role in cancer development." (PMID 38373953, 2024). "Consistency between FAK/PTK2 activity and expression exists in some cancers (3/33)." (PMID 38518034, 2024). "In addition, 2 immunotherapeutic biomarkers (TMB and MSI) are significantly correlated with FAK/PTK2 in some cancers." (PMID 38518034, 2024). "Therefore, more research on this topic is needed before the association between FAK/PTK2 and cancer immunotherapy is clearly understood and widely accepted." (PMID 38518034, 2024). "Our pan-cancer analysis further substantiated these findings, demonstrating that the downstream effects of CCDC6 and PTK2 on cell function are likely pervasive in cancer beyond just HL, a finding consistent with prior evidence showing their broader roles in cancer progression." (PMID 39697539, 2024). "Significant correlation between SCNV and expression of PTK2 was found in different cancer types." (PMID 36937870, 2023). "PTK2 is commonly overexpressed in cancer and regulates cell adhesion and migration." (PMID 35154476, 2022). "PTK2 activates Rac1 to promote invasive properties in carcinoma cells." (PMID 35456223, 2022). "Known that circRNAs mainly function by sponging target miRNAs in cancers, we hypothesized that circ-PTK2 might sponge its target miRNAs and contribute to the development and progression of MM as well." (PMID 34395238, 2021). "Multiple studies report on the importance of PTK2 for cancer progression." (PMID 33589614, 2021). "Other factors responsible for anoikis resistance and anchorage-independent cell growth are epithelial-mesenchymal transition (EMT), cancer stemness, autophagy, and integrins as well as their downstream mediators such as focal adhesion kinase (FAK, also called protein tyrosine kinase 2 (PTK2))." (PMID 33435156, 2021). "More importantly, EGFR and PTK2/FAK had the highest AUC value (0.715) among all genes, indicating that EGFR and PTK2/FAK could be suitable biomarker candidates associated with cancer progression." (PMID 33634070, 2021).